Y_RNA (Y RNA )
Gene: Miscellaneous RNA gene on chromosome 10 (121,846,600 to 121,846,700, forward strand). Ensembl gene ENSG00000201884.
Homologues: Orthologues: chimpanzee Y_RNA (93% identical). Paralogues in human: RNY3 (89% identical), Y_RNA (89% identical), RNY3P1 (88% identical), Y_RNA (88% identical), Y_RNA (87% identical), Y_RNA (86% identical), Y_RNA (85% identical), RNY3P14 (84% identical), Y_RNA (84% identical), Y_RNA (83% identical), RNY3P11 (82% identical), RNY3P7 (82% identical), and 95 more.